ENSG00000272305 (novel transcript)
Gene: Protein-coding gene on chromosome 3 (52,969,119 to 53,099,453, reverse strand). Ensembl gene ENSG00000272305.
Genetic constraint (gnomAD): Missense variants: 117 observed, 138.92 expected, observed/expected ratio (o/e) 0.84, 90% interval 0.72 to 0.98. Synonymous variants: 52 observed, 60.85 expected, observed/expected ratio (o/e) 0.85, 90% interval 0.68 to 1.08.